IL6 (interleukin 6)
Diseases named in the same sentence as IL6 in open-access papers (continued):
Sharing a sentence is not in itself a finding about the gene and the disease.
cancer (continued). "IL-6 was reported to importantly contribute in cancer growth and progression by activating IL6R-JAK-STAT3 signaling pathway." (PMID 33121520, 2020). "The enhanced macroautophagy in turn, positively regulates TG2/NF-κΒ/IL-6 signaling, thereby implying a potential positive feedback loop required for cancer cell survival." (PMID 32231206, 2020). "This is inspired by cytokine release syndrome (CRS), seen in cancer immunotherapy, which is also often treated with IL-6-blocking agents." (PMID 32838342, 2020). "Regarding IL-6, this adipocytokine stimulates angiogenesis, promotes cell proliferation, increases survival of malignant cells and inhibits cancer cell apoptosis, for example, in colon cancer." (PMID 33261185, 2020). "In the secretome of patients with advanced carcinoma, it has been possible to find a positive correlation between the secretion of IL-6, IL-1β, IL-2, and IL-4 and the concentration of MGAs." (PMID 32630302, 2020). "Taken together, these data demonstrate that the therapeutic efficacy of TGFβR2 blockade in TGFβR2‐mutant PDA is a result of the inhibition of the CAF TGFβ‐IL‐6 paracrine signal that drives cancer cell proliferation and inhibits NK cell activity." (PMID 31609088, 2019). "Therapeutic strategies targeting the IL-6 pathway are in development for cancers and inflammatory diseases." (PMID 31396215, 2019). "Inflammatory cytokines, such as tumor-necrosis factor-α (TNF-α), interleukin-6 (IL-6) and IL-8, are often upregulated and promote the invasive properties of cancer, such as angiogenesis and metastasis." (PMID 31439034, 2019). "Although the role of IL-6 in cancer development and progression is clear, studies on the serum levels of IL-6 in healthy controls and OSCC patients have shown contradictory results." (PMID 31167516, 2019). "IL-6 has a pleiotropic effect, it is elevated in the serum of cancer patients, and a systemic impact of IL-6 on the patient’s organism should be expected." (PMID 30925774, 2019). "The JAK2/STAT3/IL-6 pathway is hyperactivated in several types of cancer and important to the growth of BCSCs." (PMID 31480284, 2019). "Among the most extensively studied pro-stemness cytokines secreted by CAFs are IL-6 and IL-8, which have been shown to play an essential role in the regulation of CSCs as well as cancer invasion and metastasis." (PMID 31417869, 2019). "Meanwhile, IL-6 contributed to cancer chemoresistance by gp130/MAPK/STAT3 mediated activation of transcription factors C/EBPβ/δ, epithelial to mesenchymal transition, overexpression of p-glycoprotein and expansion of cancer stem cells." (PMID 30897064, 2019). "We have identified that inhibition of the TGFβ‐IL‐6 paracrine signaling axis reduces STAT3 activation in cancer cells and also blunts immune evasion." (PMID 31609088, 2019). "Among the various stimulators of STAT3 activation, IL-6 is a key growth factor for tumorigenesis, and its production is considered as an important factor for linking inflammation to cancer." (PMID 31816985, 2019). "IL-6 is highly upregulated in many cancers and is considered as one of the most important pro-inflammatory cytokines during tumorigenesis and metastasis." (PMID 31540047, 2019). "For example, IL6, HIST1H3C, and HIST1H3G, which were classified with high degrees are present in pathways associated with transcriptional dysregulation in cancer." (PMID 31827401, 2019). "We further observed that ODZ10117 effectively inhibited the level of tyrosine phosphorylated STAT3 in various cancer cell lines that are persistently activated or activated by IL-6-stimulation." (PMID 31684051, 2019). "NF-κB is one of the key transcription factors in cancer associated inflammation transition process, regulated via TNF and various cytokines including IL-6." (PMID 31906201, 2019). "The direct effect of IL-6 on cancer cells and other elements of the cancer ecosystem is dependent on the type of activated IL-6 receptor, which exists in membrane-bound and soluble forms." (PMID 30925774, 2019).
cancer (continued). "A new study confirms that blocking IL-6-driven inflammatory signaling can inhibit the spread of cancer cells to the liver." (PMID 31440472, 2019). "IL-6, DNMTs and cancer stemness-related genes like OCT4 usually interplay with one another to promote carcinogenesis." (PMID 31771617, 2019). "Cancer control group (CC) possessed relatively high secretion of IL-6, IFN-γ, MCP-1, IL-10, IL-12p70 and TNF-α from week 1 until week 4 compared with other groups." (PMID 30947706, 2019). "For example, most studies report that IL-6, an inflammatory cytokines, increases the proliferation of cancer cells, while studies using live or heat-killed microbes reported mixed results of IL-6 promoting or inhibiting cell growth." (PMID 31117164, 2019). "Chronically elevated circulating IL-6 has been reported in cancer patients and preclinical models of cancer cachexia." (PMID 30918582, 2019). "IL-6 has been proved to be involved in the proliferation and differentiation of various malignant tumors." (PMID 31470515, 2019). "The potential therapeutic effect of apigenin for the treatment of esophageal and other IL-6–overexpressing cancers requires further investigations." (PMID 31572184, 2019). "Findings from this study highlight the significance of IL-6-DNMT3b–mediated OCT4 expressions in future therapeutic target for patients expressing cancer stemness-related properties or sorafenib resistance in HCC." (PMID 31771617, 2019). "IL-6 can also promote survival and regeneration of damaged epithelia during inflammatory challenges, a feature that can be subverted to promote cancer progression." (PMID 31156640, 2019). "Numerous soluble mediators released from cancer cells, such as interleukin-1 (IL-1), IL-6, IL-8, M-CSF, prostaglandin-E2, tumour necrosis factor-α and, most importantly, parathyroid hormone-related protein are known to induce osteoclastic differentiation." (PMID 31217507, 2019). "Patients with malignancies (Group 1) showed increased IL-1β, IL-6, and IL-8 as well as decreased numbers of CD163+ M2 macrophages." (PMID 31366164, 2019). "The current study is the first to demonstrate the ability of natural compounds, such as MH, to bind sIL-6R and interfere with IL-6 trans-signaling in cancer cells." (PMID 31491838, 2019). "IL-6 regulates cancer stem cell, mesenchymal stem cell formation, and epithelial to mesenchymal transition in cancer, and is a contributing factor for chemoresistance." (PMID 31590252, 2019). "In this context, several studies have reported on the apparent utility of measurement of serum C-reactive protein (CRP), a surrogate for IL-6, as a strategy to predict responsiveness of cancer patients to ICI-targeted immunotherapy." (PMID 31616428, 2019). "Especially the role of IL-6, a multifunctional cytokine, with cancer, has been strongly established." (PMID 30232514, 2019). "Suppression of IL-6 production has been suggested as a therapeutic strategy for immune-mediated diseases and cancer progression." (PMID 31540502, 2019). "Aside from the molecular targeting of IL-6, IL-8 and their receptors, targeting their downstream signaling components in cancer cells and/or CSCs offer other viable opportunities for disabling the CAF–CSC crosstalk." (PMID 31417869, 2019). "Our results suggest that iCAFs induce EMT-related changes in cancer cells predominantly via the secretion of IL-6." (PMID 30744595, 2019). "IL-6 promotes tumorigenesis in a cancer cell autonomous manner as well as by influencing the differentiation of immune cells, including B cells, T cells, and myeloid cells, and by promoting immunoglobulin production by B cells." (PMID 31075939, 2019). "The IL-6 signaling pathway plays an important role in linking chronic inflammation to tumorigenesis, being directly involved in both cancer initiation and progression." (PMID 31491838, 2019). "In particular, IL-6 exerts a pro-metastatic effect in gastric SGC7901 cancer cells that show high levels of both MMP-2 and MMP-9 in conditioned medium." (PMID 31817563, 2019).
cancer (continued). "EGR3 activates related inflammatory signaling pathways (such as the NF-kb pathway) by activating the expression of IL-6 and IL-8, which are closely related to the occurrence and development of cancer." (PMID 31844579, 2019). "Previous studies have reported that autocrine secretion of IL-6 by cancer cells contributes to resistance to treatment." (PMID 30927911, 2019). "Dysregulation of inflammatory cytokine signalling is an emerging mechanism in transformation and IL-6 is over-expressed in diverse cancers, correlating with increased STAT3 activity." (PMID 31226168, 2019). "On the other hand, the extracellular IL-6–mediated JAK/STAT signaling pathway accelerates the cancer process by prohibiting autophagy." (PMID 31126310, 2019). "Fucoidan supplementation increases cancer cell death and attenuates the adverse effects of etoposide that decrease the production of the pro-inflammatory cytokine IL-6 and chemokine CCL2/MCP-1." (PMID 31041568, 2019). "IL-6-induced EMT increases cancer cell migration and invasion through the expression of MMPs in several cancer cell types." (PMID 31557902, 2019). "Interventions with JAK-STAT3 related inhibitors in a cancer cachexia model decrease IL-6 level and alleviate skeletal muscle atrophy." (PMID 31681010, 2019). "In cancer patients, increased levels of the blood cytokine (i.e., IL-1β, IL-6, and TNFα) have been recognized; however, these cytokines contribute most likely to a small portion of the abnormal metabolism." (PMID 30941358, 2019). "Previous studies have suggested that some inflammatory factors such as CRP, interleukin-6 and neutrophil to lymphocyte ratio can predict the prognosis in cancer patients." (PMID 31815279, 2019). "Those same authors also demonstrated that many other factors— including IL-6, RANTES, HGF, STAT3—implicated in the control of cancer cell growth and motility and considered targets for anticancer therapies, were downregulated after TARGIT8,44–46." (PMID 31133667, 2019). "Among studies evaluating cancer mortality outcomes in participants who were cancer-free at baseline, IL-6 and IL-8 were found to be important predictors of mortality." (PMID 31448052, 2019). "The JAK-STAT3 signaling plays a key role in anticancer immunotherapy and in cytokines such as interleukin-6 (IL-6)-mediated effects in cancer progression." (PMID 31192135, 2019). "In fact, the NF-kB/IL-6/STAT3 pathway plays an important oncogenic role in cancers that arise from chronic inflammation such as HCC." (PMID 31731457, 2019). "Particularly, autocrine IL-6 has been reported to enhance the anti-apoptosis capacity of cancer cells, which is a key mechanism of resistance to multiple therapies." (PMID 31623629, 2019). "Given that gp130 is ubiquitously expressed in many cell types, including cancer cells, trans-signaling is the predominant form of IL-6 signaling in inflammation and cancer." (PMID 31491838, 2019). "In particular, the authors identify α-SMAhigh CAFs in direct contact with neoplastic cells, while α-SMAlow CAFs localize distant from cancer cells and display a strong paracrine release of pro-inflammatory cytokines, including IL-6." (PMID 30927908, 2019). "A recent study reports that IL6 triggers the expression of VEGF promoted cancer cell multiplication." (PMID 31398937, 2019). "Findings from this study highlight the significance of IL-6-DNMT3b–mediated signaling as a potential therapeutic target for patients with HCC exhibiting cancer stemness-related properties and sorafenib resistance." (PMID 31771617, 2019). "For example, TNFα and IL-6 trans-signaling induced by the cancer cells accelerates autophagy/mitophagy in skeletal muscle, hereby promoting cachexia." (PMID 31121959, 2019). "IL-6 is a multi-functional cytokine produced by several normal and cancer cell types and significantly contributes to inflammatory diseases and cancer." (PMID 31557902, 2019).
cancer (continued). "Blockage of IL6 and IGF-1R activation disrupts expression of cancer stemness properties in vitro and in vivo, indicating that the inflammatory niche of IL6 promotes early recurrence through IGF-1R activation in patients with HBV-HCC." (PMID 31505803, 2019). "The increased IL-6 secretion by activated stellate cells strongly suggests a role in regulating cell growth in the cancer microenvironment." (PMID 30923340, 2019). "Infections by P. gingivalis and F. nucleatum have been proven to cause cancer through pathways of MMP9 and upregulation of cytokines such as TNF-α, IL-1β, and IL-6." (PMID 31297102, 2019). "YAP activity in cancer cells induces the expression of cytokines such as IL-6 (interleukin 6), CXCL5 (C-X-C motif chemokine 5), and granulocyte-macrophage colony stimulating factors that stimulate the recruitment of myeloid-derived suppressor cells (MDSCs)." (PMID 31817001, 2019). "In fact, activated CAFs further promote pleiotropic actions, such as secreting proinflammatory cytokines (IL-6 and IL-8) that govern the progression of cancer." (PMID 31142326, 2019). "In terms of cancer stemness, IL6/STAT3 signaling has been found to induce expression of the cancer stem cell (CSC) marker CD133 via interaction of STAT3 with NF-κB and HIF-1α in HCC." (PMID 31731457, 2019). "For example, STAT3 activated by IL6 directly upregulated the miR-21 and miR-181b-1, which was shown to be necessary for the epigenetic switch linking inflammation to cancer." (PMID 30927925, 2019). "This has major implications for the use of IL-6-targeting biologics, such as tocilizumab or sarilumab in rheumatologic, immune dysregulation diseases, and cancer." (PMID 31781117, 2019). "IL-6 is a well-documented pleiotropic cytokine with an established role in cancer progression and therapeutic resistance." (PMID 31443242, 2019). "To determine the effects of IL-6 on cancer stem cells, we measured by flow cytometry the expression of two colorectal CSCs markers, namely, CD44 and CD133." (PMID 30804456, 2019). "Two prominent type I cytokine families, IL-6 and IL-12, have been a recent focus in cancer research." (PMID 31681561, 2019). "STAT3 has been shown to engage in mechanisms to augment NFκB activation and maintain IL-6 expression in a number of cancers and inflammatory disorders." (PMID 31226168, 2019). "The role of ADAM17 and IL-6 trans-signaling in inflammation and cancer will therefore be reviewed in the following paragraphs." (PMID 31694340, 2019). "Then we performed the experiment to knockdown IL-6 by siRNA in the macrophages and used the macrophage conditioned media to stimulate cancer cells." (PMID 31685825, 2019). "The activity of MDSCs has been known to be activated by both IFNγ as well as TGFβ, and in cancer models their build-up is potentiated by IL-6 and IL-1β." (PMID 30881358, 2019). "Neutrophils can be recruited by the tumor through the production of cancer-related chemokines and cytokines (e.g., IL-6 and TNF)." (PMID 31817109, 2019). "Given its critical contributions to cancer progression, IL-6 signaling pathway (IL6-/IL6R/JAK/STAT3) is being actively pursued for novel cancer therapies." (PMID 32039001, 2019). "IL-6 is a versatile pro-cancer cytokine known to promote cancer survival, growth, invasion, and metastasis through multiple mechanisms." (PMID 31623629, 2019). "All these reports support our findings that IL-6 is a critical factor that is over-expressed in cancers and regulates the PI3K-Akt signaling pathway, leading to radioresistance and a worse treatment outcome." (PMID 30642292, 2019). "More cytokines are generated during the inflammation course in cancer, such as IL-6 and IL-11, and highly upregulated in many cancers." (PMID 31781655, 2019). "By deactivating the secretion of IL-6 by adipocytes and cancer cells, they managed to decrease proliferation, migration, invasion, and EMT, suggesting the paracrine role of this adipokine." (PMID 31756890, 2019).
cancer (continued). "The importance of IL-6 in pancreatic cancer is due to its release not only by cancer cells but also by stromal cells, thus leading to the progression of pancreatic intraepithelial neoplasia and the development of Pancreatic Ductal Adenocarcinoma (PDAC)." (PMID 31191652, 2019). "The UPR sculpts cancer proliferation through the cytokines like IL-6, released by the tumor infiltrating lymphocytes." (PMID 30881358, 2019). "These dying cancer cells were efficiently engulfed by BMDCs, leading to their phenotypic activation in vitro and production of IL-6 in a cell ratio-dependent manner." (PMID 31842994, 2019). "Conditioned media from TGFβ‐treated CAFs was able to increase pSTAT levels in cancer cells, which was IL‐6‐dependent and abrogated when CAFs were treated with 2GB." (PMID 31639254, 2019). "IL-6 has been shown to increase cancer stemness-related genes and properties by up-regulating DNMTs or down regulating DNMTs." (PMID 31771617, 2019). "Certain cytokines such as interleukin-6 (IL-6) are thought to play a key role in cancer progression and resistance to therapy." (PMID 31771091, 2019). "At present, two monoclonal antibodies against IL-6 are tested in various preclinical studies for cancer treatments." (PMID 31572184, 2019). "In a clinical study, the expression of IL-6 in the blood was found to be reduced in cancer patients who received the treatment of the anti-PD-L1 antibody MPDL3280A." (PMID 31640814, 2019). "IL-6, an immanent factor of cachexia-associated systemic inflammation, promotes browning, increases REE, and drives weight loss in cancer cachexia." (PMID 31921666, 2019). "Fundamentally, many other CAF-derived factors, such as matrix metallopeptidase 2 (MMP2), CXCL12, TGF-β, and IL-6, can promote the proliferation and invasion of cancer cells in various tumors." (PMID 31462327, 2019). "This suggests that the direct effect of IL‐6 on cancer cells via STAT3 activation is important during the progression of TGFβR2‐mutant tumors." (PMID 31609088, 2019). "The immune response related to cancer immunotherapy of GM-CSF, IL-6, and IL-10 notably involves modification of T-cell responses." (PMID 31754081, 2019). "Because the presence of secretory IL-6 is correlated with a poor prognosis in cancer patients, the regulation of intratumoral IL-6 is important for cancer treatment." (PMID 31019654, 2019). "High serum levels of the “immunosuppressive” cytokines in blood, like interleukin (IL)-6 and IL-10, are found to be correlated with poor prognosis, cancer stage and disease progression." (PMID 30232514, 2019). "IL-6 signaling can drive cancer progression through the transcriptional activation of target genes involved in cell cycle progression and cell survival, and via epigenetic mechanisms." (PMID 31557902, 2019). "Similar to cancer, many of these factors including TNFα, IL-6, IL-1, LIF, activin A, and myostatin activate Akt in skeletal muscle cells while stimulating muscle protein loss." (PMID 31480237, 2019). "We therefore examined the expression levels of tumor necrosis factor-α (TNF-α), interleukin-1 (IL-1), and IL-6, 3 key cytokines that contribute to cancer-induced bone pain." (PMID 31488714, 2019). "We further performed ELISA to measure the concentration of IL-6 in the culture media of the cancer cells KATO-III, MKN-28, and MKN-45, and fibroblasts." (PMID 30927911, 2019). "The IH-induced increases of IL-6 and epiregulin in VSMCs, therefore, let us speculate that IH also causes an increase of IL-6 and epiregulin, and consequently, chronic inflammation in other smooth muscle tissues, resulting in the progression of several cancers." (PMID 31159449, 2019). "Among the inflammatory cytokines, IL-1, TGF-β, and IL-6 are responsible for cancer cells proliferation and invasion through activation of NF-κB." (PMID 30642295, 2019). "IL-6 is a pleiotropic cytokine that is involved in multiple biological responses, including auto-immunity, inflammation and cancers." (PMID 30642292, 2019).